LEP (leptin)
Diseases named in the same sentence as LEP in open-access papers (continued):
Sharing a sentence is not in itself a finding about the gene and the disease.
Obesity (continued). "Although this LEP SNP is located in non-coding exon, it was found to be associated with severe obesity and increased leptin levels." (PMID 32544194, 2020). "Emerging data on the satiety hormone, leptin, points to another cause-effect relationship between obesity and vitamin D insufficiency." (PMID 32528735, 2020). "Adipose tissue production of the pro-inflammatory hormone leptin, and the role of leptin in mediating obesity-associated inflammatory disease, is the subject of this review." (PMID 33584724, 2020). "The possible underlying mechanism of increased AgRP in obesity is hypothalamic re-sistance to its function due to increased leptin concentrations in obese individuals." (PMID 31918705, 2020). "Subclinical inflammation in obesity has been associated with early insulin resistance brought upon by leptin-driven and increased levels of TNF-α and subsequent decrease in insulin receptor substrate 1 (IRS-1) signaling and tyrosine kinase activity." (PMID 32295104, 2020). "To illustrate the potential application of this method in a second disease model system, we used leptin deficient ob/ob mice (Lepob/ob), a common mouse model of obesity and type II diabetes." (PMID 33302448, 2020). "Obesity is often associated with glucose intolerance, elevated leptin, glucose and insulin blood levels, and insulin resistance." (PMID 32244932, 2020). "Previous studies have shown that obesity is associated with leptin resistance and increased blood levels of leptin with concomitant increases in SOC3, which plays a role in inhibiting signal transduction of leptin and other cytokines." (PMID 33071815, 2020). "These inflammatory factors attract macrophages to migrate to the adipose tissue, promoting the release of cytokine and obesity-associated inflammation including leptin and adiponectin." (PMID 33259491, 2020). "Obesity is closely associated with various metabolic disorders, including leptin resistance, which is characterized by high circulating leptin levels." (PMID 32846917, 2020). "In leptin-deficient mice (ob/ob mice), bulimia, obesity, and insulin resistance have been documented; these effects were reversed following a leptin injection." (PMID 33133214, 2020). "MMP-2 was described as elevated at circulating level in obese humans, and furthermore, it has been implicated in leptin resistance causing IR and obesity in mice by leptin receptor cleavage." (PMID 32214011, 2020). "These mice lack leptin due to a spontaneous homozygous mutation on the leptin gene, causing marked obesity, hyperinsulinemia, and hyperglycemia by 12 weeks of age." (PMID 32194403, 2020). "Obesity has been associated with circulating inflammatory biomarkers, including higher concentrations of leptin, C-reactive protein (CRP), interleukin (IL)-6, and tumor necrosis factor-α (TNFα), and lower adiponectin." (PMID 33259491, 2020). "Obesity-related genes impact hormones and associated peptide production, including LEP, IGF2, and IGF1, and receptors, such as IGF1R, AR, FSHR, ESR1, and LEPR." (PMID 33113859, 2020). "Mutations in the leptin or LepR gene result in severe, early onset obesity, both in animal models and in humans." (PMID 33396484, 2020). "Mutations in the FTO gene raise blood levels of leptin, a known mediator or growth factor between obesity and colon cancer, which activates a variety of pathways associated with colon cancer." (PMID 33304380, 2020). "Mutations in Lepr are associated with an obesity phenotype in mice and show elevated plasma levels of leptin, glucose, insulin and corticosterone." (PMID 31956894, 2020). "The increased absolute number of adipocytes found centrally or ectopically in obesity can lead to a sustained increase in circulating leptin, up-regulating Glut1 receptors on a variant of T-cell modulators." (PMID 33326480, 2020). "Vitamin A deficiency and increased expression of leptin, enhance the levels of pro-inflammatory cytokines that contribute to the systemic inflammation in obesity." (PMID 33195370, 2020).
Obesity (continued). "Here, we show that leptin-deficient ob/ob mice display elevated hypothalamic ER stress as early as postnatal day 10, i.e., prior to the development of obesity in this mouse model." (PMID 32313051, 2020). "In summary, obesity causes adipocyte hypertrophy, resulting in increased leptin, ER stress, hypoxia, and/or adipocyte cell death, which can lead to the secretion of inflammatory cytokines as well as the recruitment and polarization of inflammatory macrophages." (PMID 32630445, 2020). "Elevated leptin during obesity is a known risk factor and contributor to insulin resistance and glucose intolerance by suppressing proinsulin synthesis and insulin secretion." (PMID 31947955, 2020). "The disruption of elafin-dependent anti-obesity, anti-diabetic, and hepatoprotective effects in leptin-deficient ob/ob male mice reflect their absolute dependency on leptin." (PMID 32733043, 2020). "The first known adipocyte hormone, leptin, whose genetic absence causes massive obesity, suppresses appetite, while other hormones, like adiponectin, have just the opposite effect." (PMID 32962281, 2020). "Leptin resistance is a hallmark of obesity and it has been demonstrated that gut microbiota control leptin action." (PMID 32824322, 2020). "The relationship between other obesity-associated markers and semen quality parameters, serum reproductive hormones, lipids and leptin were also investigated." (PMID 32993674, 2020). "PNS-induced thermogenesis and beige cell recruitment were predominantly observed in wild-type mice but gene-deficient mice with impaired leptin pathway signaling, which indicated that the anti-obesity effects of PNS were associated with leptin activation." (PMID 33042284, 2020). "We also reported that DNAJC27 was positively associated with obesity biomarkers such as leptin and resistin." (PMID 32733386, 2020). "In middle-aged and older men (mean age between 50 and 80 years), the degree of blood leptin was positively associated with the risk of obesity onset within a few years." (PMID 33114326, 2020). "Hyperphagia and obesity can be normalized by administration of exogenous leptin to leptin-deficient human subjects or ob/ob mice." (PMID 32731387, 2020). "Leptin has been implicated in the pathogenesis of MetS, with high levels of leptin associated with the upregulation of pro-inflammatory cytokines, obesity, insulin resistance, type 2 diabetes, and cardiovascular disease." (PMID 33020413, 2020). "Leptin-stimulated tumor growth is not limited to breast cancer, but is to melanoma and prostate cancer and several other obesity-linked cancer types recently reviewed by Modzelewska and colleagues." (PMID 33019728, 2020). "Together, blood leptin is a risk factor for metabolic diseases, as well as for cardiovascular impairments, that occurs dependently or independently of obesity." (PMID 33114326, 2020). "Leptin resistance is related to diet-induced obesity (high-fat diets), which is the main cause of obesity in humans." (PMID 32967728, 2020). "Alteration in serum leptin concentration (e.g., leptin deficiency or elevated leptin level) is one of the strongest single contributors causing childhood early onset obesity." (PMID 33114326, 2020). "Apparently, circulation levels of adipokines such as leptin and adiponectin can act as biomarkers to evaluate obesity-associated complications, including low-grade inflammation." (PMID 32375340, 2020). "Selective ablation of Mfn2 from POMC neurons in mice (POMCMfn2KO) caused leptin resistance, hyperphagia, and a reduction in energy expenditure and obesity." (PMID 33240218, 2020). "A cohort study showed that obesity was associated with higher leptin, CRP, and IL-6 levels and lower adiponectin levels from age 11 years and higher endothelial markers such as E-selectin and tissue plasminogen activator (tPA), at 15 years and onwards." (PMID 33182462, 2020).
Obesity (continued). "We investigated various body composition and white adipose features by comparing the response of C57BL/6J mice with HFD-induced obesity, leptin-deficient (ob/ob) mice and leptin receptor-deficient (db/db) mice to PNS treatment." (PMID 33042284, 2020). "We evaluated the correlations between obesity-associated markers and serum reproductive hormones, lipids and leptin." (PMID 32993674, 2020). "Along with inflammation, adipokine dysregulation—specifically decreased adiponectin and increased leptin —is a hallmark of obesity in humans and in rodent models of obesity." (PMID 32823541, 2020). "Statistical analysis was performed to assess the relationship between obesity-associated markers and semen quality, serum reproductive hormones, lipids and leptin." (PMID 32993674, 2020). "Particularly, DIO1, but not DIO2 or DIO3, mRNA expression and activity was up-regulated in subcutaneous and omental adipose tissue in obesity, being positively correlated with leptin and inversely associated with SCD1 expression." (PMID 32344656, 2020). "Conversely, the risk of obesity and insulin resistance was associated with greater leptin levels (OR = 9.57; 95% CI 3.41–26.86 and OR = 13.17; 95% CI 3.68–47.10, respectively)." (PMID 33299020, 2020). "Although ERK1−/− mice have been shown to be more sensitive to insulin, diet-induced obesity mice and leptin-deficient (ob/ob) mice have elevated ERK activity." (PMID 32576931, 2020). "In hyperleptinemic diet-induced obese (DIO) mice it led to effects such as a significant decrease of food intake, increased hypothalamic leptin sensitivity, and weight loss, a promising profile for the treatment of obesity." (PMID 33374186, 2020). "Obesity is associated with increased plasma level of leptin, a protein that is released from adipose tissue to regulate body weight by decreasing appetite besides increasing metabolism and energy expenditure." (PMID 32089876, 2020). "In this study, we analyzed the relationships between obesity-associated markers and semen parameters, serum reproductive hormones, lipids and leptin in 181 Chinese infertile men." (PMID 32993674, 2020). "We also aimed to assess if the relationship between leptin levels and type 2 diabetes risk was modified by adiponectin levels, sex, obesity status, and fat distribution." (PMID 32131811, 2020). "To extend the knowledge of biological implications of IL-4 on obesity and its complications, we studied the metabolic effects of IL-4 in two mice models of obesity: Leptin deficiency and HFD." (PMID 32585823, 2020). "Deficiency in leptin, its receptor (LepR), or its downstream signaling results in hyperphagia, hyperglycemia, and obesity." (PMID 33633690, 2020). "Male and female mice and rats exposed to maternal obesity throughout gestation and lactation show increased food intake and body weight, with impaired leptin signalling caused by high neonatal leptin levels being a likely mechanism." (PMID 33184349, 2020). "In the interaction analysis, obesity status and female sex had a significant interactive effect on LEP polymorphisms related to leptin level in rs7799039 and rs2167270, respectively." (PMID 31914480, 2020). "Ob/ob mice exhibit a mutation in the leptin gene that typically results in severe obesity with hyperphagia and hyperglycemia with insulin resistance." (PMID 31837122, 2020). "Leptin affects fat and glucose metabolism and is linked to elevated free fatty acids and glucose levels in obesity and diabetes." (PMID 33123087, 2020). "Based on the pro-inflammatory effect of leptin on immune cells it is possible that obesity-associated hyperleptinemia is responsible, at least in part, for promoting the obesity-associated inflammation that leads to insulin resistance and diabetes in obesity." (PMID 33584724, 2020). "Leptin's anorectic effects, and its ability to rescue obesity in deficient states initially fuelled enthusiasm that leptin would effectively combat obesity." (PMID 33292104, 2020).
Obesity (continued). "High leptin-adiponectin ratio was associated with obesity [adjusted OR = 15.7; 95% CI (6.2–39.7)], insulin resistance [20.6 (5.2–82.1)] and the metabolic syndrome [11.2 (2.6–48.7)]." (PMID 33299020, 2020). "It should be mentioned that associations of genetic variants in UCP1 and LEP with obesity have further been replicated in cohorts of Asian ancestry." (PMID 33193685, 2020). "The adipokines adiponectin, resistin, and leptin are cytokines that have been associated with a number of health-related conditions related to obesity-induced inflammation." (PMID 33467260, 2020). "At baseline 4 subjects (4%) had low-normal levels of leptin in spite of obesity, which suggest relative leptin deficiency as a cause of obesity." (PMID 32934313, 2020). "Rare genetic variations in the leptin-melanocortin signalling pathway can severely impair appetite regulation and cause extreme obesity in early childhood." (PMID 33140236, 2020). "Leptin resistance is an important mechanism underlying the development and maintenance of obesity and is thus regarded as a promising target of obesity treatment." (PMID 32670063, 2020). "As per the results of this study, obesity was associated with increase serum leptin levels and insulin resistance." (PMID 33489589, 2020). "Obesity is associated with an increased risk of tumorigenesis, and increased leptin levels can promote tumor metastasis." (PMID 32836215, 2020). "Obese mice that are deficient in leptin (LepOb/Ob mice) that are engineered to overexpress adiponectin are protected from obesity-associated insulin resistance, despite having elevated adiposity." (PMID 32158768, 2020). "It has also been proved that the CSF serum leptin ratio decreases as BMI increases and that central infusion of leptin into obese leptin-deficient mice corrects obesity." (PMID 32947869, 2020). "ER stress was detected in the hypothalamus of leptin-deficient neonate mice (ob/ob) before the development of obesity at postnatal day 10 (P10)." (PMID 33240218, 2020). "Maternal overweight or obesity and elevated leptin plasma concentrations can cause metabolic disorders, including excessive fatness in the offspring." (PMID 32635306, 2020). "A myriad of studies has demonstrated close associations between obesity and leptin, a well-known adipocyte-derived and anti-obesity hormone." (PMID 32517169, 2020). "We further examined the anti-obesity effects of scopolin in vivo by evaluating the serum concentrations of obesity-associated hormones such as leptin and insulin." (PMID 33218042, 2020). "Mice, with a deficiency in TGF-β–activated kinase 1 (TAK1), an upstream modulator of NF-κB, in adipocytes, displayed an increased M2 ATM count in WAT, along with an enhanced resistance to HFD or leptin-deficiency-induced obesity." (PMID 32471061, 2020). "For example, obesity is associated with leptin and insulin resistance, which results in an impaired capacity of sensing the nutritional status of body disrupts the hypothalamic control of energy homeostasis." (PMID 32717793, 2020). "Increased plasma levels of CRP (p < 10 − 5), insulin (p < 10 − 4), and leptin (p < 10 − 7) showed dysmetabolic disorders associated with overweight/obesity." (PMID 32454823, 2020). "Taken together, these data suggest that loss of myeloid KLF2 promotes a leptin-resistant phenotype, likely contributing to obesity in the basal and diet-induced states." (PMID 33208733, 2020). "Adjusted model showed that higher leptin-adiponectin ratio was associated with an elevated risk of obesity, insulin resistance and low HDL-C." (PMID 33299020, 2020). "In children, high levels of leptin and insulin are often associated with low levels of adiponectin and high levels of resistin, as obesity is a condition that modulates the secretion of both adipokines, which exacerbates insulin resistance." (PMID 33266497, 2020). "Obesity is associated with high circulating leptin levels and leptin resistance in humans and rodents." (PMID 32686763, 2020).
Obesity (continued). "Obesity is associated with systemic chronic inflammation, and it induces central leptin resistance which blocks the appetite-suppressing effect of leptin and leptin resistance in adipocytes." (PMID 32215011, 2020). "Aberrant leptin (Ob) signaling, a hallmark of obesity, has been recognized to influence breast cancer (BC) biology within the tumor microenvironment (TME)." (PMID 32727138, 2020). "The obesity microenvironment demonstrates a higher leptin–adiponectin ratio, with evidence showing that leptin is associated with initiating and progressing cancer development." (PMID 32629916, 2020). "One of the first recognized actions of leptin was its ability to inhibit food intake; indeed, loss of leptin or its receptor in both sexes engenders profound obesity." (PMID 32160920, 2020). "Leptin, a 16 kDa protein composed of 167 amino acids, is a product of the LEP gene and is associated with obesity." (PMID 32899610, 2020). "Regarding the association of LEP polymorphisms with leptin levels, the interaction with obesity existed in the dominant model of rs7799039 in obese individuals and that of rs2167270 in women (interaction p = .020 and .018, respectively)." (PMID 31914480, 2020). "Animal models, in which either the leptin (ob/ob mouse) or leptin receptor (db/db mouse) genes are mutated, are characterized by profound obesity, hyperinsulinemia, and hyperglycemia." (PMID 32709161, 2020). "On the other hand, remarkably increased leptin levels were found in obese individuals, particularly in those with obesity, suggesting a positive relationship between elevated levels of leptin and the risk of psoriasis and metabolic disorders." (PMID 33597945, 2020). "This association is often cited as evidence of leptin resistance; however, the relationship between obesity and leptin resistance remains widely disputed." (PMID 32244756, 2020). "As described in previous studies, in obesity, dysfunctional adipocytes expressed excessive leptin which subsequently increased the risk of many skin tumors." (PMID 33597945, 2020). "Excessive fat, or obesity, is associated with a decrease in adiponectin and/or an increase in leptin, resistin, and tumor necrosis factor-alpha." (PMID 32498328, 2020). "It is known that leptin can regulate cholesterol-ester metabolism and the atherosclerotic process associated with obesity." (PMID 32967728, 2020). "An explanation probably lies in the fact that obese mice have obesity‐linked disorders that can further promote tumour growth, such as increase in hyperinsulinaemia or high leptin expression." (PMID 32681609, 2020). "Previously, we reported that adiponectin and leptin were associated more with obesity and less with diabetes." (PMID 32775407, 2020). "Obesity as a cancer risk factor has been linked to excessive leptin levels in the bloodstream of overweight or obese individuals." (PMID 32471192, 2020). "Another study conducted on the association between FTO gene rs9939609 polymorphism and obesity-related hormones reported that the carriers of the A-allele had higher leptin levels, but this relationship disappeared after adjustment for BMI." (PMID 31996075, 2020). "Elevated leptin levels, which are encoded by the obesity gene, have been shown to promote the proliferation and invasion of EC cells by activating a variety of signaling pathways." (PMID 32439832, 2020). "Thebest known functions of LEP are appetite reduction, enhancement of energyexpenditure, and regulation of lipid metabolism, all of which contribute toregulating obesity, an important CAD risk factor." (PMID 32049202, 2020). "Taken all together, the present studies reveled that the chronic oral administration of small-molecule Ga caused the selective leptin sensitization in the liver, resulting in significant attenuation of hepatosteatosis and hyperglycemia in obesity." (PMID 32792584, 2020). "The induction of obesity by prolonged exposure to an HFD also caused a rise in the leptin level (hyperleptinemia)." (PMID 32937828, 2020).